RAB26 (RAB26, member RAS oncogene family)
Diseases named in the same sentence as RAB26 in open-access papers (continued):
Sharing a sentence is not in itself a finding about the gene and the disease.
tumor (11 papers, 2019 to 2025). "To unveil the molecular mechanism underlying RAB26 affecting tumor proliferation and metastasis, we performed transcriptome sequencing analysis to compare transcriptome profiles between the knockdown group and the negative control group in LNCaP cells." (PMID 40821113, 2025). "In addition, the identified DEGs were closely associated with tumour immunity, and RAB26 was found to promote the proliferation of LUAD cells." (PMID 35677538, 2022). "In conclusion, RAB26 promotes the aggressive progression of PCa and stemness of tumor cells, which is an independent biomarker for the prognosis of PCa." (PMID 40821113, 2025). "The combined findings indicate that RAB26 plays a vital role in tumor development and facilitates the process of EMT." (PMID 40821113, 2025). "After 8 weeks, we found that tumors with RAB26 knockdown displayed significantly reduced growth rates compared with control tumors, and the tumor weight of the mice in the RAB26 knockdown group was significantly lower than that of the control group." (PMID 40821113, 2025). "In vivo studies revealed that the tumor growth of A549 xenograft was markedly suppressed upon RAB26 silence." (PMID 35291909, 2022). "Our results showed that RAB26 silence reduced the expression of Ki67, PCNA, MMP2 and MMP7 in xenograft tumor samples, suggesting the suppression of RAB26 silence on NSCLC growth and metastasis in vivo." (PMID 35291909, 2022). "RAB26, as a gene related to CTCs, primary tumours and metastatic lesions, promoted the proliferation of LUAD cells." (PMID 35677538, 2022). "The body weight and tumor volumes of mice in each group was monitored, and results showed that RAB26-silenced A549 xenograft tumor exhibited significantly reduced tumor volume growth than that in shRNA-NC group." (PMID 35291909, 2022). "The results revealed that control cells result in severe tumor formation in the lung; however, Rab26 significantly reduced the tumor number." (PMID 33731709, 2021). "Putting together, these results indicate that RAB26 is a major target that mediates the role of SNRPB in tumor cell growth and metastasis." (PMID 31511502, 2019). "Additionally, we demonstrated that RAB26 played a role in promoting tumor proliferation, invasion, and migration in PCa." (PMID 40821113, 2025). "In addition, to further investigate the potential biological function of RAB26 in the self-renewal of PCSCs, tumor sphere formation assays were performed." (PMID 40821113, 2025). "These differential results regarding the impact of RAB26 on tumor development may be due to potential tumor-specific differences." (PMID 40821113, 2025). "After 12 weeks, small animal live imaging showed that knocking down RAB26 could significantly reduce the level of tumor metastasis." (PMID 40821113, 2025). "Further in vivo studies confirmed the inhibitory effect of RAB26 silence on NSCLC tumor growth." (PMID 35291909, 2022). "The expression of RAB26 was increased in tumor tissues of NSCLC including LUAD and LUSC." (PMID 35291909, 2022). "In addition, RAB26 interference plasmid was also transfected into the mice to observe the changes of tumor growth." (PMID 35291909, 2022). "Previous study reported that SNRPB promotes the tumor formation of NSCLC by regulating RAB26 and SNRPB may predict response to cisplatin-based chemotherapy for NSCLC patients." (PMID 35356432, 2022). "However, the specific mechanisms and pathways of RAB26 affecting the tumour microenvironment warrant further investigation." (PMID 35677538, 2022). "In contrast, RAB26 expression levels are reduced in aggressive cancer cell lines, suggesting that activation of RAB26-autophagy-dependent pathways may prevent metastasis and tumor progression." (PMID 41108106, 2025). "The results showed that up-regulating RAB26 increased tumor spheroid size and number in PC3 cells, whereas down-regulating RAB26 decreased them in LNCaP and 22RV1 cells." (PMID 40821113, 2025).
tumor (continued). "The protein expression of RAB26, Ki67, PCNA as well as MMP2 and MMP7 in xenograft tumor tissues from each group was also determined by western blot assay." (PMID 35291909, 2022). "Microarray profiles comparing GSLCs and non-stem tumor cells (NSTCs) isolated from primary human GBM (GBM-1) showed that 4 out of 100 members in the Ras-superfamily (RAB26, RAB27B, RAB6B and ARL4C) were significantly up-regulated in GSLCs (P < 0.05)." (PMID 33403039, 2021). "Therefore, we concluded that RAB26 might help CTCs to evade immune surveillance and promote LUAD progression by regulating immune cell infiltration in the tumour microenvironment." (PMID 35677538, 2022).
cancer (6 papers, 2019 to 2025). A tumor composed of atypical neoplastic, often pleomorphic cells that invade other tissues. "Next, to validate the anti-cancer effect of RAB26 silence on NSCLC in vivo, A549 NSCLC cells xenograft animal model was established." (PMID 35291909, 2022). "Of note, SRNPB and RAB26 both showed similar expression trends across different stages of LUAD carcinomas, further corroborating the positive correlation between SNRPB and RAB26 in NSCLC, and which is consistent with our TMA analysis." (PMID 31511502, 2019). "To explore the aberrant signaling that RAB26 may be involved in PCa, we performed GSEA to evaluate cancer-relevant signaling pathways, which are regulated by RAB26 expression alterations in PCa." (PMID 40821113, 2025). "Recently, RAB26 has received increasing attention in cancer research." (PMID 40821113, 2025). "Whether SMAD3 could target RAB26 in other cancer cells to regulate cancer progression is of worth exploring." (PMID 35291909, 2022). "To validate whether SMAD3 down-regulation was required for RAB26 silence-mediated anti-cancer effect on NSCLC, we additionally overexpressed SMAD3 in RAB26-silenced A549 cells to observe the changes in malignant processes." (PMID 35291909, 2022). "In accordance with our speculation, the anti-cancer effect of RAB26 silence on NSCLC cells was markedly abolished by SMAD3 overexpression." (PMID 35291909, 2022). "Nevertheless, the role of Rab26 in cancer deserves further examinations." (PMID 33731709, 2021). "There is evidence that SNRPB may promote the tumorigenic potential of NSCLC by regulating Rab26 expression; however, little is known about how Rab26 functions in cancer cells." (PMID 33731709, 2021). "Therefore, the role of RAB26 in cancer deserves further study." (PMID 40821113, 2025). "As a result, our study not only uncovered the oncogenic role of RAB26 in NSCLC, but also identified a novel target for SMAD3-mediated cancer progression." (PMID 35291909, 2022). "Moreover, analysis of the Cancer Genome Atlas database by GEPIA revealed that RAB26 is significantly higher in NSCLC tissue compared with normal tissue, we therefore selected RAB26 for further validation." (PMID 31511502, 2019).
infection (2 papers, 2023 to 2024). The state of being infected such as from the introduction of a foreign agent such as serum, vaccine, antigenic substance or organism. "A rescue experiment revealed that insulin secretion was reduced upon replenishing Rab26 by infection of Ad-Rab26 in Rab26-KO INS-1 cells." (PMID 37289842, 2023).
inflammation (1 paper, 2019). Aberrant reaction of the microcirculation characterized by movement of fluid and leukocytes from the blood into extravascular tissues. "Basal Rab26 maintains the balance between the two receptors through modulating cell surface receptor expression, which may be a potential therapeutic target for preventing endothelial barrier disruption and vascular endothelial inflammation." (PMID 31182932, 2019).
RAB26 also shares sentences with these, for which no sentence is quoted: acute lung injury (1 paper); acute respiratory distress syndrome (1); colorectal cancer (1); Epstein-Barr virus infection (1); pancreatic cancer (1); triple-negative breast carcinoma (1).